CBFB (core-binding factor subunit beta)
Diseases named in the same sentence as CBFB in open-access papers (continued):
Sharing a sentence is not in itself a finding about the gene and the disease.
leukemia (37 papers, 2006 to 2026). A malignant (clonal) hematologic disorder, involving hematopoietic stem cells and characterized by the presence of primitive or atypical myeloid or lymphoid cells in the bone marrow and the blood. "Core inding factor (CBF) leukemia subtypes, which includes leukemias harboring fusion genes CBFB/MYH11 or RUNX1/RUNX1T1, are associated with younger age and range from 20% in pediatric to less than 5% in older AML patients." (PMID 34947882, 2021). "We have previously shown that CBFβ is associated with ribosomal RNA genes during mitosis in leukemia cells during mitosis." (PMID 32655837, 2020). "Exon 8 frameshift mutations were highly associated with CBFB/MYH11-rearranged leukemia, while point mutations affecting position D816 were correlated with RUNX1/RUNX1T1 leukemia." (PMID 31896782, 2020). "Several leukemia-causing mutations, such as K83E, R139Q and R174Q, were found to have a reduced DNA binding affinity, but they retain the ability to bind CBFβ." (PMID 31048839, 2019). "CBFβ is the most frequently mutated and rearranged gene in human leukemias and plays an important role in hematologic malignancies." (PMID 31610798, 2019). "RUNX1 and CBFB are frequent targets of gene rearrangements through chromosomal translocations and mutations that are associated with human leukemias." (PMID 31817911, 2019). "This idea has been proposed to explain the unexpected finding that CBFβ-SMMHC fusions with reduced RUNX1 binding retain the ability to cause leukemia." (PMID 27542261, 2016). "Expression of CBFβ-SMMHC is causative for leukemia development, but the molecular mechanisms underlying its activity are unclear." (PMID 27542261, 2016). "Moreover, only CBFβ-SMMHC variants able to enhance the DNA binding affinity by RUNX1 could induce leukemia in mouse models." (PMID 40763310, 2025). "Thus, the beneficial RUNX1 mutant could counteract a leukemia-causing RUNX1 that reduces the amount of CBFβ." (PMID 31048839, 2019). "This aligns with our previous findings, highlighting the transactivation role of CBFβ-SMMHC in the development of leukemia." (PMID 40763310, 2025). "Our recent data suggested that Runx1 is indispensable for Cbfb-MYH11–induced leukemogenesis, functioning cooperatively with CBFβ-SMMHC to regulate critical genes for leukemia initiation." (PMID 40763310, 2025). "The results suggested that the C-terminal domain, especially the multimerization domain, is important for CBFβ-SMMHC to induce leukemia." (PMID 40763310, 2025). "All together, these results suggest that enhancing RUNX1’s DNA binding affinity is a critical step for CBFβ-SMMHC-induced leukemia." (PMID 40763310, 2025). "It has been shown by many groups, including ours, that CBFβ-SMMHC sequesters most RUNX1 to the cytoplasm, supporting a dominant-negative model for CBFβ-SMMHC–induced leukemia development." (PMID 40763310, 2025). "Ro5-3335, a small-molecule inhibitor (SMI) developed to target the RUNX1-CBFβ interaction, can treat leukemia by blocking the RUNX1/CBFβ transactivation." (PMID 38286983, 2024). "The ELN also stipulates suitable molecular biomarkers, highlighting leukemia initiating variants (e.g., NPM1, CBFB::MYH11, RUNX1::RUNX1T1, PML::RARA) essential in disease monitoring." (PMID 38891959, 2024). "The identified variants have been reported in AML, displaying variable effects on RUNX1 protein functions, including CBFB dimerization and DNA binding, in addition to leukemia transformation." (PMID 32782381, 2021). "Although CBFβ has been shown to play crucial roles in leukemia, the correlation between CBFβ and clinicopathological features has not been extensively analyzed in solid tumors." (PMID 31610798, 2019). "CBFβ-SMMHC dominantly represses AML1 function, generates defects in definitive hematopoiesis, and predisposes mice to leukemia with cooperating gene mutations." (PMID 31817911, 2019).
leukemia (continued). "CBFβ-SMMHC alone causes defects in hematopoietic differentiation, but additional cooperating mutations are required for transformation to frank leukemia." (PMID 27542261, 2016). "Although the mechanism of RUNX1 activity is currently not understood, these results demonstrate a genetic requirement for Runx1 for efficient CBFβ-SMMHC induced leukemia in mice." (PMID 27542261, 2016). "Surprisingly, mice expressing CBFβ-SMMHC d179-221 rapidly develop leukemia, with significantly reduced latency as compared to mice with full length CBFβ-SMMHC." (PMID 27542261, 2016). "A second possible explanation for the accelerated leukemia development by the CBFβ-SMMHC d179-221 mutant is that it alters the amount of RUNX1 available to non-fusion protein complexes." (PMID 27542261, 2016). "Studies in mice show that decreased RUNX2 activity slows CBFβ-SMMHC induced leukemia, while increased RUNX2 expression accelerates it." (PMID 27542261, 2016). "To date, two different small molecule inhibitors of the fusion protein have been identified, both of which are able to kill CBFβ-SMMHC expressing leukemia cells." (PMID 27542261, 2016). "RUNX1 and CBFB are frequent targets of chromosomal abnormalities in hematopoietic malignancies, particularly in leukemia (also referred to as CBF leukemia or CBFL)." (PMID 23344057, 2013). "The RUNX1 requirement for leukemias with CBFβ and MLL translocations further supports the idea that RUNX1 may actually promote the growth of many types of leukemia cells." (PMID 39450904, 2025). "DNA binding by RUNX1 drives CBFβ-SMMHC–induced leukemia in mice." (PMID 40763310, 2025). "Within this dataset, genes such as CBFB, SEPTIN9, CBFA2T3, CD1A, and ERG have been previously reported to be closely associated with leukemia development and progression. qPCR analysis further confirmed the reduced expression levels of these genes in IRF2BP2‐knockdown cells." (PMID 39454110, 2024). "Loss of wildtype CBFβ is expected to allow more RUNX1 to act in complexes with the fusion protein or with other transcription factors, and perhaps the activity of these other complexes accelerates the development of leukemia." (PMID 27542261, 2016). "Currently the mechanism of accelerated leukemia development caused by the CBFβ-SMMHC d179-221 mutant is not known." (PMID 27542261, 2016). "Importantly, pharmacological inhibition of either factor is effective at specifically targeting CBFβ-SMMHC expressing leukemia cells, with little effect on normal hematopoietic cells." (PMID 27542261, 2016). "Importantly, initial trials demonstrate that small molecules targeting these binding partners are effective against CBFβ-SMMHC induced leukemia." (PMID 27542261, 2016). "This confirms the importance of RUNX1 in CBFβ-SMMHC-expressing leukemia cells." (PMID 27542261, 2016). "Importantly, treatment with the HDAC8 inhibitor 22d, an ortho-Aryl-N-hydroxycinnamide, selectively induced apoptosis in mouse and human CBFβ-SMMHC expressing leukemia cells." (PMID 27542261, 2016). "Indeed, previous work has shown that proliferation of the human leukemia cell line ME-1 can be inhibited by compounds that disrupt the interaction between Runx1 and CBFβ." (PMID 20591170, 2010). "However, chimeric mice expressing CBFβ-SMMHC with deletion of the HABD (CBFβ-SMMHC-ΔHABD) only partially rescued the hematopoiesis phenotype, and unexpectedly accelerated leukemia development caused by CBFβ-SMMHC, challenging the importance of RUNX1 for CBFβ-SMMHC–mediated leukemogenesis." (PMID 40763310, 2025). "Similarly to RUNX1, CBFB is also a target of chromosome rearrangements in leukemia." (PMID 23344057, 2013). "Our lab previously showed that HDAC1 is required for active transcription of RUNX1 target genes in a mouse model of CBFβ::SMMHC (CM) driven AML, making leukemia cells particularly sensitive to the HDAC1 inhibitor, entinostat." (PMID 41214140, 2026).
leukemia (continued). "The pathogenesis of these leukemias critically involves an interaction between the transcription factors RUNX1 and CBFB, which represents a promising target for new targeted therapies." (PMID 41155189, 2025). "Other key leukemia-specific hits include MYB, MED13L, HOXA10, and the binding partner of RUNX1, CBFB." (PMID 34088716, 2021). "Exposure of HSCs to non-cytotoxic doses of BZ have caused ruptures of DNA structures at breakpoint hot stops in the leukemia-related genes MLL and CBFB similar to those found in leukemia patients." (PMID 32977499, 2020). "In summary, our study provides a detailed overview of cooperating mutations in one of the largest adult CBF leukemia cohorts so far and highlights fundamental differences between CBFB/MYH11- and RUNX1/RUNX1T1-rearranged leukemia." (PMID 31896782, 2020). "CBFB and ZNF384 are cancer genes for leukemia; RB1 is a gene for retinoblastoma, sarcoma and small-cell lung cancers and MAP3K4 is a gene for pancreatic, breast and colorectal cancers, as listed on the Cancer Gene Census." (PMID 33087126, 2020). "Based on the lead compound, they found that AI-10-49 selectively binds to CBFβ-SMMHC and disrupts its binding to RUNX1, which thus restores RUNX1 transcriptional activity, displays favorable pharmacokinetics and delays leukemia progression in mice." (PMID 34691990, 2019). "Accordingly, reduction of Runx1 or Runx2 expression inhibited CBFβ–SMMHC-mediated differentiation block in embryos and leukemia onset in mice." (PMID 29755956, 2018). "In frank leukemia, knockdown of RUNX1 or its co-factor CBFβ results in cell death suggesting sustained requirement for RUNX1 activity which is recapitulated by chemical perturbation using an allosteric CBFβ-inhibitor." (PMID 36411286, 2022). "Notably, CBFB-overexpression in MV4-11 cells conferred proliferative advantage and resistance to Ara-C (cytarabine), a widely-used first line clinical anti-leukemia drug." (PMID 29192243, 2017). "Together, these findings indicate that high affinity binding of RUNX1 is not required for CBFβ-SMMHC induced leukemia." (PMID 27542261, 2016). "Remarkably, KIT is often overexpressed in CBF leukemia concomitantly with miR-222-221 downregulation, suggesting that miR-222-221 may be under the transcriptional control of CBF (i.e., RUNX1 and CBFB)." (PMID 23344057, 2013). "In addition, mice expressing CBFβ-SMMHC with missense mutations in the C-terminal multimerization domain (mDE), which impairs the multimerization but leaves the transcriptional repression domain intact, did not develop leukemia." (PMID 40763310, 2025). "Importantly, we provide direct evidence that RUNX1 binding to target DNA is critical for leukemogenesis by CBFβ-SMMHC, since CBFβ-SMMHC could not induce leukemia in mice with a heterozygous Runx1-R188Q mutation." (PMID 40763310, 2025). "In leukemia the single cell functional plasticity of the RUNX1-miR-221-KIT axis that regulates normal proliferation and differentiation can be undermined not only by the RM8 fusion protein, but also by genetic mutations, including other non-random cytogenetic rearrangements affecting RUNX1 or CBFB." (PMID 29156756, 2017). "This indicates that CBFβ-SMMHC has effects on gene expression that are not due to loss of the RUNX1 activity, and that RUNX1 repression-independent activities may be important for leukemia development." (PMID 27542261, 2016). "Finally, we show that CBFβ-SMMHC could not induce leukemia in mice with a Runx1-R188Q mutation, which reduces RUNX1 DNA binding but does not affect its interaction with CBFβ-SMMHC or its sequestration to cytoplasm by CBFβ-SMMHC." (PMID 40763310, 2025). "We found that the binding affinity between RHD and its target DNA oligonucleotide was significantly enhanced in the presence of CBFβ-SMMHC and CBFβ-SMMHC-ΔHABD (which can induce leukemia), but not of CBFβ-SMMHC-mDE (which cannot induce leukemia)." (PMID 40763310, 2025).
leukemia (continued). "To determine the role of this coiled-coil region for leukemogenesis in vivo, we generated mice expressing knocked-in CBFβ-SMMHC with a 95–amino acid C-terminal truncation (including the coiled-coil region), and these mice failed to develop leukemia." (PMID 40763310, 2025). "Because Ro5-3335 inhibits RUNX1 and not just the CBFβ-SMMHC fusion protein, it may also be useful for the treatment of other leukemia subtypes that require RUNX1 activity." (PMID 27542261, 2016).
gastric cancer (13 papers, 2018 to 2024). A primary or metastatic malignant neoplasm involving the stomach. "As shown in our previous study, the LINC01234/miR-204-5p/CBFB axis promotes cells proliferation in gastric cancer (GC)." (PMID 35248073, 2022). "For example, LINC01234 acts as a ceRNA to regulate CBFB expression by sponging miR-204-5p to promote gastric cancer cell proliferation." (PMID 33658048, 2021). "Moreover, LINC01234 promotes cells proliferation in vitro and tumor growth in vivo by acting as a competing endogenous RNA (ceRNA) for miR-204-5p and regulating core-binding factor β (CBFB) expression in gastric cancer (GC)." (PMID 34327141, 2021). "LINC01234 acts as a ceRNA to modulate CBFB expression in gastric cancer by absorbing miR-204-5p." (PMID 32110804, 2020). "Moreover, LINC01234 could serve as ceRNA to regulate core-binding factor β (CBFB) expression by sponging miR-204-5p to regulate the apoptosis, growth arrest and tumorigenesis in gastric cancer." (PMID 33088626, 2020). "For example, in gastric cancer, LINC01234 functions as an miR-204-5p sponge to up-regulate the expression of CBFB." (PMID 35765893, 2022). "As expected, expression levels of AICDA, NFκB p65, CBFβ, APOBEC3A, and APOBEC3B were increased in gastric cancers with higher TNM stage." (PMID 30514953, 2018). "In gastric cancers, mRNA expression levels of AICDA, NFκB p65, CBFβ, APOBEC3A, and APOBEC3B were markedly increased, similar to their expression profiles in gastric mucosae with H, pylori infection." (PMID 30514953, 2018). "Secondly, although LINC01234 functioned as ceRNA to regulate CBFB expression by sponging miR-204-5p in gastric cancer, we did not identify any miRNAs as direct targets of LINC01234 to investigate whether LINC01234 was a ceRNA for miRNAs in ccRCC." (PMID 33088626, 2020). "In non-neoplastic gastric mucosae and gastric cancer tissues, expression levels of CBFβ, NFκB p65, APOBEC family, and AICDA were increased in the cases with reduced or loss of NKX6.3 expression while NKX6.3 expression was inversely correlated with expression of these genes." (PMID 30514953, 2018). "Results showed that expression levels of NKX6.3, CDH1, CDKN1A, and EP300 were decreased while expression levels of NFκB p65, AICDA, CBFβ, APOBEC3A, APOBEC3B, RhoA, ROCK1, ROCK2, PIK3CA, and CCND1 were increased in CagA positive gastric cancers compared to those in CagA negative cases." (PMID 30514953, 2018).
eosinophilia (10 papers, 2016 to 2026). "Some extremely rare fusion genes, such as CSNK2A1::PDGFRB, CBFB::MYH11, and NSD3::NUTM1, have been identified in patients with eosinophilia using RNA−seq techniques." (PMID 38992589, 2024). "However, emerging evidence suggests that a subset of patients estimated at approximately 15% of CBFB::MYH11 AML cases may present without significant eosinophilia, complicating morphological diagnosis." (PMID 41300735, 2025).
colorectal cancer (8 papers, 2009 to 2025). A primary or metastatic malignant neoplasm that affects the colon or rectum. "It increases the activities of CNOT3 in HCT-116 Colorectal cancer cell line (0.20), CBFB in ME-1 Leukaemia cell (0.13), H3K36me3-marked transcription in Left Ventricle (0.12) and Adipose Nuclei (0.12), and H3K-27me3-marked repression in Astrocyte (0.12)." (PMID 40656995, 2025). "CBFβ was characterized by its biological function in promoting cell migration and invasion in colorectal cancer cells, and the modulation depended on RUNX2." (PMID 37108164, 2023). "In colorectal cancer, CBFB deletion enhances cell resistance to MEK inhibitors." (PMID 35428233, 2022). "In colorectal cancer, the cell proliferation markers Ki-67 and PCNA were downregulated upon RUNX2 silencing, and RUNX2 was required for CBFβ-elicited cell proliferation." (PMID 37108164, 2023). "Mechanistically, RUNX2 and CBFβ form a transcriptional complex that binds to promoters and contributes to the upregulation of downstream genes, including OPN, FAM129A, and UPP1, in colorectal cancer HCT116 cells." (PMID 37108164, 2023). "In colorectal cancer, RUNX2 influences MAP kinase signaling via regulation of multiple RTKs, and its absence, can lead to resistance against MEK inhibitors along with its cofactor CBFB." (PMID 39876058, 2025).
acute promyelocytic leukemia (7 papers, 2009 to 2025). An aggressive form of acute myeloid leukemia (AML), characterized by arrest of leukocyte differentiation at the promyelocyte stage, due to a specific chromosomal translocation t(15;17) in myeloid cells. "Several studies have reported that acute promyelocytic leukemia (APL) has a molecular “signature” associated with the presence of the PML-RARα gene fusion, which is distinct from the signatures of AMLs expressing AML1-ETO, CBFβ-SMMHC or C/EBPα mutations." (PMID 19352456, 2009). "Assays have been developed for three phenotypes of particular clinical significance: NPM1, Core Bind Factor (CBF)-AML (referring to the fusions gene RUNX1::RUNX1T1 and CBFB::MYH11) and Acute Promyelocytic Leukemia (APL) (referring to the fusion gene PML::RARA)." (PMID 35892893, 2022). "Importantly, PCR assays have been developed for three AML phenotypes: (i) acute promyelocytic leukemia (APL) (fusion gene PML::RARA); (ii) patients with NPM1 and CBF–AML (RUNX1::RUNX1T1 and CBFB::MYH11); and (iii) AML with fusion genes BCR::ABL1, KMT2::MLLT3, and DEK::NUP214." (PMID 37345204, 2023).
osteoarthritis (7 papers, 2021 to 2024). A noninflammatory degenerative joint disease occurring chiefly in older persons, characterized by degeneration of the articular cartilage, hypertrophy of bone at the margins and changes in the synovial membrane. "We found that Cbfβf/fAggrecan-CreERT mice with Cbfβ-deficiency in articular cartilage developed a spontaneous osteoarthritis-like phenotype with articular cartilage degradation." (PMID 38617544, 2024). "We recognized 22 of these genes as druggable according to the DGIdb database, such as MTF1, KLC3, STAT3, LIFR, and CBFB, making them potential targets for osteoarthritis therapy." (PMID 39796139, 2024). "Adding our current findings to our previous research, we can now piece together a more complete picture of Cbfβ’s role across the entire spectrum of cartilage development in osteoarthritis." (PMID 38805545, 2024). "In our current study, the Col2a1-CreERT system allowed us to investigate Cbfβ’s role not only in mature chondrocytes but also in early chondroprogenitor cells, offering a comprehensive view of Cbfβ’s involvement in cartilage in osteoarthritis." (PMID 38805545, 2024). "Our results provide new insights into how Cbfβ regulates Wnt canonical signaling during OA pathogenesis which may lead to novel therapies for the treatment of degenerative joint diseases." (PMID 38805545, 2024). "Therefore, the use of the Cbfbf/f;Col2a1-CreERT mouse mutant strain was instrumental in expanding our understanding of Cbfβ’s multifaceted role in osteoarthritis, highlighting its importance not only in mature cartilage but also in the early stages of cartilage formation and differentiation." (PMID 38805545, 2024). "Thus, it was speculated that abnormally increased expression of Cbfβ in the cartilage tissue of osteoarthritis might play an important regulatory role upstream of the pathogenic pathway." (PMID 33573620, 2021). "Such a small molecule, kartogenin, binds to FLNA, disrupting its interaction with the transcription factor core-binding factor β subunit (CBFβ), and induces chondrogenesis by regulating the CBFβ-RUNX1 transcriptional program in osteoarthritis." (PMID 39195282, 2024).